SLCO2A1 (solute carrier organic anion transporter family member 2A1)
Diseases named in the same sentence as SLCO2A1 in open-access papers (continued):
Sharing a sentence is not in itself a finding about the gene and the disease.
SLCO2A1 also shares sentences with these, for which no sentence is quoted: breast carcinoma (3 papers); Hyperglycemia (3); Arthritis (2); chronic gastritis (2); enteropathy (2); follicular carcinoma (2); hepatic carcinoma (2); acute kidney injury (1); amenorrhea (1); asthma (1); atopic dermatitis (1); autoimmune disease (1); autosomal recessive primary hypertrophic osteoarthropathy 1 (1); bowel obstruction (1); brain tumor (1); chronic granulomatous disease (1); coeliac disease (1); connective tissue disorder (1); depressive disorder (1); diverticular disease (1); enterocolitis (1); Eosinophil enteritis (1); essential hypertension (1); follicular thyroid adenoma (1); ghosal hematodiaphyseal dysplasia (1); graft versus host disease (1); Granuloma (1); hemorrhage (1); Hepatic fibrosis (1); infectious disease (1).
A further 17 diseases each share a sentence with SLCO2A1 in 1 paper.